TNF (tumor necrosis factor)
Diseases named in the same sentence as TNF in open-access papers (continued):
Sharing a sentence is not in itself a finding about the gene and the disease.
colitis (continued). "Researchers found that IL-18 mRNA and TNF-α mRNA levels were elevated in DSS-induced colitis, and the administration of pralnacasan significantly reduced the expression of IL-18 mRNA but did not affect the expression of TNF-α mRNA." (PMID 31242947, 2019). "GSVA indicated that the CSF-1 gene set was enriched in TCT colitis, only weakly and non-significantly impacted by anti-TNFα therapy, but robustly normalized following treatment with JNJ-40346527." (PMID 31710624, 2019). "Besides, ALA, EPA, and DHA were demonstrated to reduce the expression of TNF-α, LTB4, and COX-2 by inhibiting NF-κB activity in rats with TNBS-induced colitis." (PMID 31780872, 2019). "The replacement of E. faecalis wild type strain by a Δeut mutant resulted in exacerbated colitis in SIHUMI colonized IL-10−/− mice, as indicated by increased histological inflammation, increased tissue expression of TNF and IL-12p40 and increased spleen weights." (PMID 31281321, 2019). "DSS-colitis model mice produced high levels of the proinflammatory cytokines IL-1β, IL-6 and TNF-α, and B. adolescentis IF1-03 mice produced lower IL-1β, IL-6 and TNF-α, and elevated levels of the anti-inflammatory IL-10, compared to the DSS-colitis model and B. adolescentis IF1-11 protection mice." (PMID 30987344, 2019). "Previous reports showed that in an animal model of colitis, mice treated with CTX present an up regulation of local anti-inflammatory cytokines, such as TGF-β and IL-10, and a decreased expression of proinflammatory cytokines, such as IL-6 and TNF-α." (PMID 31757011, 2019). "In contrast, the gene expression profile in AGMs moderately correlated to colitis models and cytokine stimulation (including type I and II interferons, but not TNF-α) from the previremic stage, throughout the course of infection." (PMID 31704931, 2019). "Similarly, L. reuteri treatment also decreased the serum levels of the inflammatory cytokines KC, TNF-a, IFN-γ, and IL-6 in the DSS colitis mice." (PMID 31214189, 2019). "Both the CSF-1 and the TNFα gene sets were enriched in the colonic mucosal transcriptomes of Crohn’s disease and in mouse colitis, and expression of both gene sets was highest in patients who did not respond to anti-TNFα therapy." (PMID 31710624, 2019). "Standard management for those with severe colitis includes administration of systemic corticosteroids with the reservation of antitumor necrosis factor (anti-TNF) therapy, such as infliximab, if there has been no improvement." (PMID 31428491, 2019). "In our study, we found that thalidomide treatment in modeling or after modeling could reduce the overexpression of Th cell (Th1 and Th17) cytokines including IFN-γ, IGF-1, IL-6, IL-17 and TNF-α in serum and intestinal tissues in TNBS-induced colitis model." (PMID 31920668, 2019). "Further, although mice treated with IL-1β neutralising antibodies display reduced DSS inflammation and expression of IL-6 mRNA transcripts, TNF levels are unaltered, indicating that IL-1β may play a more dominant role in promoting DSS colitis than TNF." (PMID 30542349, 2018). "Additionally, the production of TNF-α and IL-1β is significantly inhibited after oral administration of LycogenTM in mice with DSS-induced colitis or renal injury." (PMID 29642620, 2018). "Given that mast cell mediators such as proteases and TNF are well-known to directly increase intestinal permeability, the increased permeability in DKO mice is likely secondary to the increased severity of DKO colitis." (PMID 29849494, 2018). "The lack of cross-species reactivity of V565 with murine TNFα precluded an evaluation of the efficacy of V565 in a mouse model of colitis." (PMID 29563546, 2018). "A marked increase in colonic levels of TNF-α and LTB4 at 24 h was observed in the colitis." (PMID 29494494, 2018). "TNF-α, IL-6, and IFN-γ are the main inflammatory mediators in murine colitis models." (PMID 30289911, 2018).
colitis (continued). "Furthermore, while VSL#3 increased the production of the proinflammatory cytokine TNF-α in SAMP mice, we found that GWT inhibited the production of TNF-α and IL-12 in macrophages stimulated with LPS as well as TNBS-induced colitis." (PMID 29862296, 2018). "In the mouse model, oral administration of KM1608 significantly improved DSS-induced colitis symptoms, such as disease activity index (DAI), colon length, and colon weight, as well as suppressed the expression of IL-6, TNF-α, and myeloperoxidase (MPO) in the DSS-induced colitis tissues." (PMID 30126158, 2018). "Furthermore, we found that GWT significantly suppresses the production of cytokines such as TNF-α and interleukin-12 (IL-12) in macrophages and in the colon of rats with TNBS-induced colitis." (PMID 29862296, 2018). "However, administration of GWT to rats with TNBS-induced colitis reduced TNF-α mRNA expression by about 50%, indicating that GWT significantly inhibits TNF-α mRNA expression in vivo." (PMID 29862296, 2018). "Nevertheless, the present study showed similar results to a previous study which used a similar colitis model, where IL-17A levels were not influenced by the presence of TNFα and IL-1β." (PMID 30127744, 2018). "Delivery of anti-TNFα Nanobody, anti-TNFα Affibody, trefoil factors and elafin, by recombinant L. lactis, have demonstrated effectiveness in DSS-induced colitis animal model of IBD." (PMID 29966384, 2018). "IL-6, CSF3, TNF-α, and IL-17 were also induced in the colon of DSS-treated WT mice compared to untreated animals; the levels of induction were comparable to those observed in C. rodentium colitis." (PMID 29922289, 2018). "WT mice with acute colitis had increased serum levels of IL-6 compared to WT mice, but the serum level of TNF-α was not different." (PMID 29540173, 2018). "In the present study, the LC27 and LC67 mixture PM, synergistically rather than additively, attenuated TNBS-induced colitis such as colon shortening, myeloperoxidase activity, TNF-α and IL-10 expression, and Th17 and Treg cell differentiation." (PMID 29760423, 2018). "Moreover, fortunellin (5 or 80 mg/kg) reversed the excessive pro-inflammatory cytokine (TNF-α, IL-1β, and IL-6) profiles and MPO activity in the TNBS-induced colitis model." (PMID 29472916, 2018). "Colon IL-6 production was significantly lower in n-3 and n-6 groups compared to TNBS group (P < 0.05 for both) while colon TNFα production did not significantly differ among colitis groups but tend to decrease in n-3 group compared to TNBS group (P = 0.0617)." (PMID 29670469, 2018). "Partially hydrolyzed guar gum (PHGG), a water-soluble NSP produced from guar gum beans through enzymatic hydrolysis, ameliorated colonic damage and decreased MPO activity, TNF-α protein, and mRNA expression in the colonic mucosa in a TNBS-induced colitis model." (PMID 28654020, 2017). "While cibinetide did not affect erythropoiesis, it reduced the influx of myeloid cells into the lamina propria and inhibited the local production and systemic availability of TNF, IL-6, IL12/IL-23, myeloid derived chemokines and nitric oxide (NO) in mice suffering from DSS colitis." (PMID 29026145, 2017). "Levels of TNF-α, IL-4 and IL-6 mRNA were significantly increased in the DSS model group compared with the healthy control group, indicating that DSS significantly increased intestinal inflammation in the DSS-induced colitis mouse model." (PMID 29162986, 2017). "In addition, oroxylin A down-regulated the production of NF-κB downstream targets, including TNF-α and IL-6, in DSS-induced colitis mice." (PMID 28938606, 2017). "Seven days after colitis induction, the extent of inflammation in the colon was assessed by measuring neutrophil infiltration (MPO activity), proinflammatory cytokine levels (TNF-α and IL-1β), and inflammation parameters." (PMID 29123119, 2017).
colitis (continued). "Interestingly, PSMP increases were observed in the initial stage in the DSS-induced colitis model; at this time, CCL2, IL-6 and TNF-α were still expressed at low level." (PMID 28698550, 2017). "Our ex vivo findings discount a role of TNF-α in the suppression of NHE-2 in the experimental colitis (data not shown)." (PMID 28493993, 2017). "Overall, the miRNA profile of IL10−/− mice treated with the anti-TNFα therapy was intermediate between those of the non-inflamed group (D28) and the colitis group (D98, PBS treated)." (PMID 28566745, 2017). "This study has generated a successful model of colitis that remains TNFα non-responsive and has demonstrated that IL-1β expression is a major pathway for the progression of colitis in this system." (PMID 28796256, 2017). "However, they also showed that CS exposure increased mRNA expression of inflammatory cytokines including TNF, IFN-γ, IL-17, and IL-21 in Ja18−/− mice and escalated clinical symptoms of DSS-induced colitis in CD1d−/− mice." (PMID 29163466, 2017). "Exercise significantly decreased macroscopic and microscopic colitis, substantially increased CBF and attenuated the plasma TNF-α, IL-6, MCP-1, IL-1β and leptin levels while raising the plasma irisin and the plasma and WAT concentrations of adiponectin in HFD mice (p < 0.05)." (PMID 28425943, 2017). "Serum IL-1β was not increased in TNFα KO Winnie (data not shown), suggesting that systemic secretion of IL-1β was low, perhaps due to the early age and level of colitis." (PMID 28796256, 2017). "We found that the levels of active IL-1β and IL-18, which are induced by the inflammasome, but not IL-6 and TNF-α, were associated with increased FLC and inflammatory damage in colitis tissues or tumor formation in AOM/ DSS-induced CAC." (PMID 28701727, 2017). "A value of mucosal concentration of TNF-α was around a three-fold larger than mucosal concentration of TNF-α in the colon of control animals without colitis." (PMID 27598133, 2016). "Transgenic mice expressing only membrane bound TNF-α, in the absence of soluble TNF-α, exhibited colitis, suggesting important physiological role of the dual TNF-α signaling." (PMID 27415000, 2016). "Administration of Mutaflor after induction of colitis was without significant effect on mucosal concentration of IL-1β or TNF-α in the colon." (PMID 27433160, 2016). "With the exception of modest, but significant increase of mucosal TNFα expression, 13 days post-transfer Rag2-/- mice did not develop overt signs of colitis." (PMID 27050757, 2016). "Beside T-cell activation, which is a prerequisite for the development of colitis in this model, macrophage-expressed SLAMF2 could contribute to colitis by inducing TNF-α production, as suggested by in vitro experiments." (PMID 26834746, 2016). "Consistent with alleviated colitis in REGγ−/− mice, ELISA analysis of colonic explants revealed less production of pro-inflammatory cytokines and chemokines including KC, MIP2α, CXCL5, IL-1β, IL-6 and TNFα in REGγ−/− mice than in WT counterparts." (PMID 26899380, 2016). "Furthermore, in a rat model of TNBS-induced colitis, diet supplemented with ALA decreased the number of lesions, normalized colon induced NO synthase (iNOS) and COX-2 expression and lowered levels of TNF-α and leukotriene B-4 (LTB-4) to baseline." (PMID 27990120, 2016). "Following treatment with H-SN1 for 7 days after the attack of colitis, an amelioration in the clinical manifestations and histological signs became apparent, as assessed by the colon length change, DAI and histological scores, and the level of TNF-α." (PMID 27158082, 2016). "In the present study, CaA could significantly reverse the increase of IL-6, TNFα and IFNγ in DSS colitis mice." (PMID 27177331, 2016). "Lack of elevated IL-6 and TNFα in the colon of AOM/DSS treated mice indicates that the mucosa is almost completely recovered from colitis during 2-week recovery period." (PMID 26951793, 2016).
colitis (continued). "Mucosal levels of AnxA1 increased in the absence of TNF-α signaling, allowing early recovery of colitis as compared to wild-type (WT) mice." (PMID 27199985, 2016). "Sodium butyrate ameliorated histological colitis and decreased levels of tumor necrosis factor (TNF)-α and IL-6 in IL-10−/− mice compared with those without treatment." (PMID 27886121, 2016). "We investigated whether 2-Cl-IB-MECA administration alters the production of pro-inflammatory cytokines, including TNF-a and IL-1β, in colon epithelia of DSS colitis mice." (PMID 25762375, 2015). "IBD and DSS induced colitis are characterized by elevated levels of proinflammatory cytokines including IFN-γ, TNF-α and IL-6, and also increased NO production, which contribute to the destruction of the epithelium, ulceration of the intestinal mucosa, erosion and infiltration of inflammatory cells." (PMID 25844068, 2015). "Specifically, mice with proximally spread, but not distally contained, colitis have increased IL-1β, IL-6, IL-17, TNFα, and IFNγ combined with decreased IL-10 in the distal colon." (PMID 26121642, 2015). "In our study, the RT-PCR assay exhibited that the mRNA levels of TNF-α, IL-1β, and IL-6 were greatly reduced by CBS in DSS-induced colitis mice, suggesting that the protective effect of CBS against colonic injury is related to the regulation of TNF-α, IL-1β, and IL-6." (PMID 26579201, 2015). "Additionally, ELISA showed that the serum levels of IFN-γ, TNF-α, IL-12, IL-6, and IL-1β were down-regulated in a TNBS model of colitis." (PMID 26561804, 2015). "Additionally, during TNBS-induced colitis, mice treated with α2-adrenoceptor antagonist, RX821002, showed a reduced expression of colonic proinflammatory genes (TNF-α and IL-1β)." (PMID 26635804, 2015). "In our study, we found that the mRNA levels of TNF-a and IL-1β increased in the DSS colitis mice." (PMID 25762375, 2015). "It is well established that the level of cytokines, such as TNF-α, is elevated during experimental colitis, while there were no changes in TNF-α level observed in this study." (PMID 25079872, 2014). "Notably, ERCs attenuated colitis with significantly reduced DAI, decreased levels of intra-colon IL-2 and TNF-α, but increased expressions of IL-4 and IL-10." (PMID 25475342, 2014). "However, TNFα which is a dominant player in the pathogenesis of IBD induces an acute process of inflammation, which probably only mimics the active phase of colitis." (PMID 25276054, 2014). "Our efforts in the study of pathogenesis of IBD have shown that TNF is expressed mainly by F4/80+ macrophages rather than CD4+ T cells in the DSS colitis model." (PMID 24520376, 2014). "It is worth to note, however, that a recent study on a mouse model of T cell-mediated colitis has shown that only neutralization of the transmembrane, but not soluble, TNF form induced remission of experimental colitis." (PMID 25045210, 2014). "Our previous results in a total body knockout for SK1 demonstrated that SK−/− mice with DSS-induced colitis exhibited an exaggerated TNFα response but failed to induce COX2 in colon tissue." (PMID 25460165, 2014). "However, a long-term treatment of colitis by 5-ASA and anti-TNF displays intolerance and side effects, such as nausea, allergy, pancreatitis, and hepatitis." (PMID 24995035, 2014). "Compared with the TNBS model group, the DAI scoring, plasma and colonic mucosa Hcy levels, MPO activity and contents of MDA, IL-1β, IL-6, TNF-α, MMP-2, MMP-9 in colon and EB in small intestine were significantly increased in the TNBS-induced colitis rats with simultaneous Hcy injection (P < 0.01)." (PMID 24787389, 2014). "In summary, βGalT1-overexpressing mice are resistant to TNF-induced SIRS and DSS-induced colitis." (PMID 24339869, 2013). "For example, a certain anti-TNF monoclonal antibody has been reported to be effective in TNBS-induced colitis but not in OXN-induced colitis." (PMID 24348533, 2013).
colitis (continued). "In addition, this compound decreased serum levels of tumor necrosis factor (TNF)-α and interferon (IFN)- γ in a concentration-dependent manner in mice with experimental colitis." (PMID 24340073, 2013). "Analyses of specific T-cell regulatory cytokines (TNF-α, IL-4, IFN-γ, IL-17, TGF-β, IL-12) revealed that WCHF treatment can suppress the Th1 and Th17, but not Th2, responses in colon tissues and dendritic cells of DSS-induced colitis mice." (PMID 23734189, 2013). "The cytokine profile and histopathology of murine DSS-colitis has similarities with both forms of IBD, namely elevation of pro-inflammatory cytokines, such as TNFα and IFNγ, transmural inflammation, and aphthous erosions (like CD) as well as increased levels of IL-4 and crypt abscesses (like UC)." (PMID 23468885, 2013). "Next, we analyzed whether this altered microbiota composition is protective in inflammation models by subjecting CT and TG mice to TNF-induced SIRS, a model in which the gut is a crucial target and DSS-induced colitis." (PMID 24339869, 2013). "Both TNF and mucin might be selectively altered before epithelial cell damage in DSS-induced colitis, one of the most comprehensively tested models of colitis that mimics the clinical and histological features of human UC." (PMID 23723167, 2013). "In addition, we found increased level of inflammatory cytokines and chemokines such as TNF-α and MIP-2 in colon and serum of colitis mice." (PMID 23826144, 2013). "In addition, the overproduction of numerous inflammatory mediators such as IL-1β, IL-6, tumor necrosis factor (TNF)-α, as found in cultures of mice with colitis." (PMID 22400037, 2012). "As well as ameliorating H. typhlonius-induced colitis in TRnUC mice, TNF-α blockade also substantially reduced colonic Il17a transcripts, consistent with the possibility that TNF-α-augmented IL-17A production is physiologically relevant in ILC-mediated colitis." (PMID 23063332, 2012). "To assess the role of TNFα in hepcidin regulation in vivo, we injected wild-type mice without colitis with the recombinant cytokine and found, consistent with the results in the Huh7 cells, that hepcidin expression was significantly reduced." (PMID 22675442, 2012). "Using the SCID adoptive transfer colitis model, we have evaluated the effect of currently used IBD drugs and IBD drug candidates, that is, anti-TNF-α, TNFR-Fc, anti-IL-12p40, anti-IL-6, CTLA4-Ig, anti-α4β7 integrin, enrofloxacin/metronidazole, and cyclosporine." (PMID 22536543, 2012). "TNF-α and IL-1β involved in the development of DSS-induced colitis in mice." (PMID 23159923, 2012). "The protective effects of TNF during acute phases of gut inflammation are further supported by a study reporting that TNF deletion in mice leads to increased severity and exacerbation of disease in acute DSS-induced colitis." (PMID 22848704, 2012). "The levels of TNF-α and IL-1β were significantly raised in DSS-induced colitis." (PMID 23159923, 2012). "Severity of colitis was evaluated by disease activity index (DAI), body weight (BW) change, colon length, histology, myeloperoxidase (MPO) activity, and proinflammatory cytokine production including tumor necrosis factor-α (TNF-α) and interferon-γ (IFN-γ)." (PMID 22647055, 2012). "Since DSS-induced colitis is partially mediated by IEC apoptosis, an alternative hypothesis is that TNF inhibits IEC apoptosis, thus improving overall intestinal barrier function." (PMID 22848704, 2012). "Taken together with the data on colitis severity (e.g. histologic scores), these data clearly show that TNF is not required for development of clinically significant severe colitis in Il10−/− mice." (PMID 22848611, 2012). "In contrast to the prevention studies, intervention therapy with anti-TNF-α did not consistently ameliorate colitis in this model." (PMID 22536543, 2012). "Instead, mice with either no TNF (T/I) or reduced ability to produce TNF (T-het/I) spontaneously developed colitis under clean, helicobacter-free conditions." (PMID 22848611, 2012).